VMO1 (vitelline membrane outer layer 1 homolog)
Synonyms: ERGA6350; PRO21055
Tractability: Antibody: UniProt places it where antibodies can reach, with high confidence; UniProt predicts a signal peptide or a membrane-spanning region; its Gene Ontology location is reachable by antibodies, with medium confidence.
Gene: Protein-coding gene on chromosome 17 (4,785,285 to 4,786,433, reverse strand). Ensembl gene ENSG00000182853.
Subcellular location: Secreted
Gene Ontology:
Cellular component: extracellular exosome; extracellular region
Genetic constraint (gnomAD): Loss-of-function variants: 13 observed, 11.6 expected, observed/expected ratio (o/e) 1.12, 90% interval 0.73 to 1.73. The upper end of that interval is the gene's LOEUF score, 1.73, which puts it in group 6 of 6, group 1 being the genes least tolerant of losing a copy. Missense variants: 304 observed, 289.35 expected, observed/expected ratio (o/e) 1.05, 90% interval 0.96 to 1.15. Synonymous variants: 117 observed, 126.78 expected, observed/expected ratio (o/e) 0.92, 90% interval 0.79 to 1.08.
Homologues: Orthologues: chimpanzee VMO1 (98% identical), macaque VMO1 (90% identical), dog VMO1 (76% identical), mouse Vmo1 (71% identical), rat Vmo1 (70% identical), guinea pig VMO1 (69% identical), pig VMO1 (62% identical), tropical clawed frog vmo1 (47% identical), zebrafish vmo1b (44% identical), zebrafish vmo1a (44% identical), Caenorhabditis elegans vmo-1 (34% identical), Caenorhabditis elegans txt-3 (33% identical), and 12 more.
Diseases named in the same sentence as VMO1 in open-access papers:
VMO1 is named in the same sentence as 4 diseases in open-access papers, as found by Europe PMC text mining. Sharing a sentence is not in itself a finding about the gene and the disease. The quoted sentences say what the papers report.
osteosarcoma (1 paper, 2019). A usually aggressive malignant bone-forming mesenchymal neoplasm, predominantly affecting adolescents and young adults. "A combination of eight genes (RAB1,CLEC3B,FCGBP,RNASE3,MDL1,ALOX5AP,VMO1 and ALPK3) were identified as being associated with osteosarcoma metastasis." (PMID 30868060, 2019).
ovarian carcinoma (1 paper, 2023). A malignant neoplasm originating from the surface ovarian epithelium. "Also, chicken VMO1 is abundant in ovarian carcinomas of laying hens and is regulated by estrogen and microRNAs in the chicken oviduct." (PMID 36680395, 2023). "Thus, chicken VMO1 may be a potential biomarker of ovarian carcinomas." (PMID 36680395, 2023).
bacterial infection (1 paper, 2023). "Vmo1 is a protein that separates the yolk from the egg, is located in the outer layer of the egg white vitelline membrane, and protects the embryo against bacterial infection." (PMID 37824467, 2023).
VMO1 also shares sentences with these, for which no sentence is quoted: tumor (1 paper).